CABS1 (calcium binding protein, spermatid associated 1)
Description:
Calcium-binding protein (By similarity). Essential for maintaining the structural integrity of the sperm flagella (By similarity).
Synonyms: C4orf35; NYD-SP26; FLJ32897; CLPH
Tractability: No criterion of Open Targets' tractability assessment is met for any kind of drug.
Gene: Protein-coding gene on chromosome 4 (70,334,981 to 70,337,116, forward strand). Ensembl gene ENSG00000145309.
Subcellular location: Cytoplasm; Mitochondrion inner membrane; Cell projection, cilium, flagellum; Cytoplasmic vesicle, secretory vesicle, acrosome
Gene Ontology:
Molecular function: calcium ion binding
Biological process: flagellated sperm motility; spermatogenesis
Cellular component: acrosomal vesicle; cytoplasm; mitochondrial inner membrane; motile cilium; sperm principal piece
Genetic constraint (gnomAD): Loss-of-function variants: 1 observed, 1.28 expected, observed/expected ratio (o/e) 0.78, 90% interval 0.23 to 1.86. That is too few expected variants to judge how well the gene tolerates losing a copy. Missense variants: 500 observed, 490.39 expected, observed/expected ratio (o/e) 1.02, 90% interval 0.95 to 1.1. Synonymous variants: 195 observed, 179.12 expected, observed/expected ratio (o/e) 1.09, 90% interval 0.97 to 1.23.
Homologues: Orthologues: chimpanzee CABS1 (99% identical), macaque CABS1 (93% identical), dog CABS1 (66% identical), pig CABS1 (62% identical), mouse Cabs1 (61% identical), rat Cabs1 (60% identical).
Diseases named in the same sentence as CABS1 in open-access papers:
CABS1 is named in the same sentence as 7 diseases in open-access papers, as found by Europe PMC text mining. Sharing a sentence is not in itself a finding about the gene and the disease. The quoted sentences say what the papers report.
epididymitis (1 paper, 2021). Inflammation of the epididymis. "We found that Ccnyl1 expression was elevated; however, Sept4 and Krt1 were reduced in sperm from cauda epididymitis, indicating that the expression of flagella-related proteins was disturbed in Cabs1 KO mice." (PMID 33440775, 2021).
infertile (1 paper, 2021). "Additionally, although the total abnormal sperm rate was higher in the caput epididymis, no statistical difference was found in sperm from the cauda epididymis in infertile compared with fertile Cabs1 KO mice." (PMID 33440775, 2021). "In addition, a disrupted capacity of Ca2+, Mg2+, and Zn2+ of Cabs1 may, to some extent, explain the infertility in Cabs1 KO mice, but this should be further investigated." (PMID 33440775, 2021). "Hence, we propose that the sperm with a normal appearance may be dysfunctional in some way in Cabs1 KO infertile mice." (PMID 33440775, 2021).
Sjogren syndrome (1 paper, 2024). An autoimmune disorder in which immune cells attack and destroy the glands that produce tears and saliva. "Connecting hCABS1 to a potential anti-inflammatory role in humans, it has been reported that in Sjogren’s syndrome, an autoimmune inflammation of the salivary glands, CABS1 mRNA levels were decreased 5.4-fold in comparison to normal." (PMID 38753592, 2024).
teratospermia (1 paper, 2021). "The teratospermia may contribute to the impaired fertility observed for Cabs1 KO males." (PMID 33440775, 2021).
cancer (2 papers, 2024 to 2026). A tumor composed of atypical neoplastic, often pleomorphic cells that invade other tissues. "Our immunofluorescence studies did not detect obvious differences in CABS1 abundance between SMG from Sjogren’s subjects or normal tissue regions from surgical resections for cancer." (PMID 38753592, 2024).
CABS1 also shares sentences with these, for which no sentence is quoted: male infertility (2 papers); prostate carcinoma (1).